SLC35C1 (solute carrier family 35 member C1)
Description:
Antiporter specific for GDP-l-fucose and depending on the concomitant reverse transport of GMP. Involved in GDP-fucose import from the cytoplasm into the Golgi lumen.
Synonyms: FUCT1; FLJ11320; CDG2C
Tractability: Antibody: UniProt predicts a signal peptide or a membrane-spanning region. PROTAC: its protein half-life has been measured.
Gene: Protein-coding gene on chromosome 11 (45,804,072 to 45,813,016, forward strand). Ensembl gene ENSG00000181830.
Subcellular location: Golgi apparatus membrane
Subcellular location (Human Protein Atlas): Golgi apparatus
Pathways (Reactome):
Disease: Defective SLC35C1 causes congenital disorder of glycosylation 2C (CDG2C)
Metabolism of proteins: GDP-fucose biosynthesis
Transport of small molecules: Transport of nucleotide sugars
Gene Ontology:
Molecular function: GDP-fucose transmembrane transporter activity; protein binding
Biological process: GDP-fucose import into Golgi lumen; GDP-L-fucose biosynthetic process; 'de novo' GDP-L-fucose biosynthetic process; GDP-L-fucose salvage
Cellular component: Golgi apparatus; Golgi membrane
Genetic constraint (gnomAD): Loss-of-function variants: 8 observed, 21.75 expected, observed/expected ratio (o/e) 0.37, 90% interval 0.22 to 0.66. The upper end of that interval is the gene's LOEUF score, 0.66, which puts it in group 2 of 6, group 1 being the genes least tolerant of losing a copy. Missense variants: 422 observed, 472.47 expected, observed/expected ratio (o/e) 0.89, 90% interval 0.82 to 0.97. Synonymous variants: 226 observed, 224.62 expected, observed/expected ratio (o/e) 1.01, 90% interval 0.9 to 1.12.
Gene-disease validity (ClinGen):
ClinGen rates the evidence that SLC35C1 causes each of these diseases.
leukocyte adhesion deficiency type II (autosomal recessive): Strong. Leukocyte adhesion deficiency type II (LAD-II) is a form of LAD characterized by recurrent bacterial infections, severe growth delay and severe intellectual deficit.
Homologues: Orthologues: chimpanzee SLC35C1 (99% identical), macaque SLC35C1 (97% identical), dog SLC35C1 (93% identical), rabbit SLC35C1 (92% identical), pig SLC35C1 (90% identical), guinea pig SLC35C1 (88% identical), mouse Slc35c1 (88% identical), rat Slc35c1 (88% identical), tropical clawed frog slc35c1 (72% identical), zebrafish slc35c1 (65% identical), Caenorhabditis elegans nstp-10 (53% identical), Drosophila melanogaster nac (46% identical), and 1 more. Paralogues in human: SLC35E4 (19% identical), SLC35D1 (17% identical), SLC35D2 (17% identical), SLC35E2B (17% identical), SLC35H1 (17% identical), SLC35E3 (16% identical), SLC35E1 (15% identical), SLC35D3 (13% identical), SLC35D4 (12% identical).
Diseases named in the same sentence as SLC35C1 in open-access papers:
SLC35C1 is named in the same sentence as 28 diseases in open-access papers, as found by Europe PMC text mining. Sharing a sentence is not in itself a finding about the gene and the disease. The quoted sentences say what the papers report.
colon cancer (6 papers, 2020 to 2023). "Taken together, these results indicate that SLC35C1 is a negative regulator of the canonical Wnt pathway, and loss of SLC35C1 promotes colon cancer progression through the activation of the Wnt signalling pathway." (PMID 31961998, 2020). "Taken together, these data indicate that down‐regulation of SLC35C1 in colon cancer induces Wnt pathway activity, whose over‐activation has been proved to be a hallmark of colon cancer." (PMID 31961998, 2020). "SLC35C1 has been uncovered to abrogate the progression of colon cancer via inactivation of Wnt pathway." (PMID 35668364, 2022). "In conclusion, we identified SLC35C1 as a negative regulator of the Wnt signalling pathway in colon cancer." (PMID 31961998, 2020). "Down-regulation of SLC35C1 in colon cancer induces Wnt pathway activity, whose overactivation has been proved to be a hallmark of colon cancer." (PMID 32655399, 2020). "We show here that SLC35C1 is reduced in all colon cancer by both immunohistochemistry images and TCGA data, whereas β‐catenin is increased." (PMID 31961998, 2020). "Immunohistochemistry images of colon cancer tissues and study of the TCGA (The Cancer Genome Atlas) database both implied the reduction of SLC35C1 and elevation of β‐catenin in all stages of colon cancer." (PMID 31961998, 2020). "In summary, we identified SLC35C1 as a novel negative regulator of the canonical Wnt pathway, and SLC35C1 is reduced in colon cancer." (PMID 31961998, 2020). "Immunohistochemistry assay revealed that SLC35C1 expression is significantly decreased in colon cancer, whereas β‐catenin is increased." (PMID 31961998, 2020). "This study also offers the potential to explore drugs that can restore SLC35C1 to reduce Wnt activity and to prevent colon cancer progression." (PMID 31961998, 2020). "In the previous study, SLC35C1 is a negative regulator of the Wnt signaling pathway in gastrointestinal cancer and colon cancer." (PMID 32655399, 2020). "SLC35C1 is a negative regulator of Wnt signalling in colon cancer." (PMID 33836758, 2021). "Therefore, we wish to determine the level of SLC35C1 and β‐catenin in colon cancer tissue and control tissue." (PMID 31961998, 2020). "Some recent studies have shown that SLC35C1 is found to be a negative driver of the classical Wnt pathway in colon cancer species and that deletion of SLC35C1 promotes colon cancer progression by activating the Wnt signaling pathway." (PMID 37005450, 2023).
leukocyte adhesion deficiency (5 papers, 2015 to 2021). Leukocyte adhesion deficiency (LAD) is a primary immunodeficiency characterized by defects in the leukocyte adhesion process, marked leukocytosis and recurrent infections. "Mutation of SLC35C1 was found to cause leukocyte adhesion deficiency, which was a rare congenital disease due to the defect in the biosynthesis of selectin ligands on leukocytes." (PMID 35087752, 2021). "Leukocyte adhesion deficiency type II (LADII) is caused by impaired glycoconjugate fucosylation due to impaired function of SLC35C1, the GDP-fucose transporter, and is therefore named SLC35C1-CDG under the current nomenclature of glycosylation disorders." (PMID 34567084, 2021). "Interestingly, adult Gfus−/− mice developed neutrophilia and a LAD (leukocyte adhesion deficiency)‐like defect comparable to what is seen in humans with SLC35C1‐CDG." (PMID 34468083, 2021).
leukocyte adhesion deficiency type II (5 papers, 2015 to 2024). "Thus, SLC35C1-CDG, also called Leukocyte Adhesion Deficiency type II (LAD-II), shows impairment of leukocyte migration and homing due to decreased expression of selectin ligands, with subsequent propensity for infections." (PMID 38550576, 2024). "Mutations of the human GDP-fucose transporter gene SLC35C1 cause the rare disease leukocyte adhesion deficiency type 2 (LAD II), or congenital disorder of glycosylation SLC35C1-CDG, characterized by severe immunodeficiency, psychomotor defects, delayed mental development, and slow growth." (PMID 38270391, 2023). "Absence of sLex, as seen in patients with SLC35C1 mutations, results in impairment of this process and leukocyte adhesion deficiency type 2 (discussed separately)." (PMID 26125015, 2015).
hepatocellular carcinoma (3 papers, 2021 to 2024). A malignant tumor that arises from hepatocytes. "We previously reported higher fucosylation levels in HepG2 cells than in other hepatoma cell lines due to the increased expression of SLC35C1 mRNA, which encodes GFT." (PMID 36313594, 2022). "have reported that SLC35C1, as a GDP-fucose transporter, was highly expressed and with an increased level of fucosylation in hepatocellular carcinoma." (PMID 35087752, 2021). "Additionally, elevated SLC35C1 expression is known to be a key factor for increased fucosylation in hepatocellular carcinoma (HCC), and thus could be a potential target for the treatment and diagnosis of HCC." (PMID 39718015, 2024).
Immunodeficiency (3 papers, 2020 to 2023). Failure of the immune system to protect the body adequately from infection, due to the absence or insufficiency of some component process or substance. "severe immunodeficiency accompanied by a skeletal dysplasia in PGM3-CDG; immunodeficiency with the Bombay blood phenotype and severe growth and psychomotor retardation in leukocyte adhesion deficiency type II (known as SLC35C1-CDG)." (PMID 34540767, 2021). "LAD type 2 (LAD2) is caused by mutations in the SLC35C1 gene leading to a generalized loss of expression of fucosylated glycans on the cell surface and LAD type 3 (LAD3) is caused by mutations in the FERMT3 gene resulting in platelet function defects along with immunodeficiency." (PMID 33391282, 2020). "Recurrent and severe infections as a part of immunodeficiency phenotype were reported in ALG12-CDG, ATP6AP1-CDG, EXTL3-CDG, G6PC3-CDG, MOGS-CDG, PGM3-CDG, and SLC35C1-CDG." (PMID 34540767, 2021).
colorectal cancer (2 papers, 2020 to 2023). A primary or metastatic malignant neoplasm that affects the colon or rectum. "Decreased SLC35C1 may cause over‐activation of Wnt signalling in colorectal cancer." (PMID 31961998, 2020). "This is further supported by detecting SLC35C1 mRNA level in the tissue samples using real‐time PCR, which showed that the mRNA level of SLC35C1 is reduced in stage 3 and stage 4 colorectal cancer." (PMID 31961998, 2020). "The results showed that the mRNA level of SLC35C1 decreased in stage 3 and stage 4 colorectal cancer." (PMID 31961998, 2020). "Down‐regulation of SLC35C1 is also detected by real‐time PCR in stage 3 and stage 4 colorectal cancer tissues." (PMID 31961998, 2020). "In this study, we found that the expression of SLC35C1 decreased in colorectal cancer, which is different from previous studies, suggesting that SLC35C1 may be a potential prognostic marker." (PMID 37005450, 2023). "Moreover, to investigate the relationship between SLC35C1 expression and β‐catenin level, we analysed the TCGA provisional database including 640 colorectal cancer samples with cBioPortal." (PMID 31961998, 2020).
congenital disorder of glycosylation (2 papers, 2017 to 2025). Congenital disorder of glycosylation (CDG) is a fast growing group of inborn errors of metabolism characterized by defective activity of enzymes that participate in glycosylation (modification of proteins and other macromolecules by adding and processing of oligosaccharide side chains). "L-Fucose administration to SLC35C1-CDG (congenital disorders of glycosylation) patients via their daily food intake reduces immunological and other clinical symptoms, potentially by allowing the utilization of the external source of sugar through a poorly characterized salvage pathway." (PMID 28925387, 2017). "However, oral fucose supplementation has proven to be an effective therapy for SLC35C1-CDG (LAD II) and GFUS-CDG patients with defects in GDP-fucose transportation or de novo synthesis (CDG: congenital disorders of glycosylation)." (PMID 40286076, 2025).
glioma (2 papers, 2023 to 2024). A benign or malignant brain and spinal cord tumor that arises from glial cells (astrocytes, oligodendrocytes, ependymal cells). "Based on SLC35C1 expression, a risk factor model was found to predict OS of glioma." (PMID 37005450, 2023). "Finally, we established a risk factor pattern based on SLC35C1 expression could predict OS of glioma." (PMID 37005450, 2023). "The inhibition of SLC35C1 in glioma cells increased tumor cell proliferation, migration, and invasion." (PMID 39718015, 2024). "The results displayed that in glioma, the high expression of SLC35C1 was mainly concentrated in TNFA_SIGNALING_VIA_NFKB, GLYCOLYSIS, APICAL_JUNCTION and other signaling pathways." (PMID 37005450, 2023). "Construction of Pklv2-SLC35C1 plasmid for the establishment of glioma cell lines stably overexpressing SLC35C1." (PMID 37005450, 2023). "The effect of overexpression of SLC35C1 on glioma cell proliferation was examined by CCK8 assay, and the results showed that SLC35C1 overexpression significantly promoted cell proliferation." (PMID 37005450, 2023). "To further investigate the role of SLC35C1 in the migration and invasion of glioma cells, we performed knockdown and overexpression of SLC35C1." (PMID 37005450, 2023). "We further constructed the WGCNA network according to glioma data to explore the regulatory network related to SLC35C1 in glioma." (PMID 37005450, 2023). "The results of EdU assay and Plate clone formation assay showed that overexpression of SLC35C1 significantly promoted the proliferation and colony formation of glioma cells." (PMID 37005450, 2023). "Subsequent Quantitative real-time PCR further confirmed that the expression of SLC35C1 was significantly increased in glioma tissues." (PMID 37005450, 2023). "Therefore, it is clinically important to further investigate the expression profile of SLC35C1 in human tumors to provide new molecular clues for the pathogenesis of glioma." (PMID 37005450, 2023). "Finally, we made a prediction model based on SLC35C1 expression and clinical symptoms to predict the prognosis of glioma, and further constructed its regulatory mechanism in glioma progression, and confirmed that SLC35C1 was highly expressed in glioma." (PMID 37005450, 2023). "Therefore, we performed in vitro experiments to validate the results and showed that knockdown and overexpression of SLC35C1 have completely opposite effects on glioma cell genesis and development." (PMID 37005450, 2023). "Quantitative real-time PCR was taken to detect the expression of SLC35C1 in glioma tissues." (PMID 37005450, 2023). "Finally, the results of in vitro experiments showed that the silencing and overexpression of SLC35C1 had completely opposite effects on the physiological activity of glioma cells." (PMID 37005450, 2023). "According to the findings of the Cox regression analyses, this study further constructed a nomogram based on the age, grade, and the expression of SLC35C1, to create a quantitative method for clinicians to predict the probability of 1‐ and 2‐year OS in glioma patients." (PMID 37005450, 2023). "In addition, we found that SLC35C1 gene silencing and gene overexpression had opposite effects on the biological behaviour of glioma cells." (PMID 37005450, 2023). "Also, fluorescence quantitative PCR further confirmed the high expression of SLC35C1 in glioma patients." (PMID 37005450, 2023). "Functional bioinformatics analysis indicated that SLC35C1 may be involved in multiple signaling pathways and biological processes in glioma." (PMID 37005450, 2023). "In addition, in vitro experiments showed that SLC35C1 knockdown significantly inhibited the proliferation, migration and invasive ability of glioma cells, while SLC35C1 overexpression promoted proliferation, migration, invasion and colony formation of glioma cells." (PMID 37005450, 2023). "In addition, we constructed a glioma cell line stably overexpressing SLC35C1." (PMID 37005450, 2023).
glioma (continued). "Finally, quantitative real-time PCR confirmed that SLC35C1 was highly expressed in gliomas." (PMID 37005450, 2023). "The effect of silencing SLC35C1 on glioma cell proliferation was examined by CCK8 assay, which presented that SLC35C1 knockdown significantly inhibited cell proliferation." (PMID 37005450, 2023). "Enrichment analysis shows that SLC35C1 may act mainly through signaling pathways such as TNFA_SIGNALING_VIA_NFKB, GLYCOLYSIS, and APICAL_JUNCTION thus affecting glioma development and progression." (PMID 37005450, 2023).
cholangiocarcinoma (1 paper, 2025). A carcinoma that arises from the intrahepatic biliary tree (intrahepatic cholangiocarcinoma) or from the junction, or adjacent to the junction, of the right and left hepatic ducts (hilar cholangiocarcinoma). "FX and GDP-fucose transmembrane transporter (solute carrier family 35 member C1/SLC35C1) were discovered to contribute to the aberrant fucosylation in intrahepatic cholangiocarcinoma." (PMID 40821120, 2025).
colon adenocarcinoma (1 paper, 2020). "Consistently, analysing data collected from The Cancer Genome Atlas (TCGA) with online tool UALCAN (http:// ualcan.path.uab.edu/index.html) revealed that SLC35C1 level is decreased in primary (P = .0004) and all four stages of colon adenocarcinoma (COAD, P = .0002.0003.0057.0075, respectively." (PMID 31961998, 2020).
epilepsy (1 paper, 2021). A brain disorder characterized by episodes of abnormally increased neuronal discharge resulting in transient episodes of sensory or motor neurological dysfunction, or psychic dysfunction. "Additionally, seizures or epilepsy (SLC35C1, FCSK‐CDG, FUT8‐CDG) and immunological phenotypes (SLC35C1‐CDG) have been reported." (PMID 34468083, 2021).
fungal infection (1 paper, 2020). "For example, a defective innate immune (what happens in SLC35C1-CDG) or humoral response is associated with bacterial infections, while T-cell defects underlie viral and fungal infection susceptibility." (PMID 32635232, 2020).
Intellectual disability (1 paper, 2024). "In particular, SLC35C1-CDG IIc patients, carrying mutations in the GDP-fucose transporter, which limits the biosynthesis of sLeX and other fucosylated glycans, display moderate to severe intellectual disability and microcephaly." (PMID 38197965, 2024).
lung adenocarcinoma (1 paper, 2023). A carcinoma that arises from the lung and is characterized by the presence of malignant glandular epithelial cells. "To explore the correlation between fucosylation and PD-L1 expression, we knocked out the GFT-encoding gene SLC35C1 in mouse Lewis lung adenocarcinoma cells and in human H1299 lung adenocarcinoma cells." (PMID 37928424, 2023). "Loss of SLC35C1 decreased the migration of Lewis lung adenocarcinoma cells." (PMID 37928424, 2023). "To assess whether fucosylation regulates PD-L1 expression in LUAD, we established SLC35C1 gene-knockout Lewis lung adenocarcinoma cells (Lewis-KO) using the CRISPR/Cas9 genome editing system." (PMID 37928424, 2023). "In addition, we knocked down SLC35C1 in human lung adenocarcinoma H1299 cells (H1299-KD)." (PMID 37928424, 2023).
lung carcinoma (1 paper, 2023). "Our data suggests that loss of SLC35C1 suppresses lung cancer cell migration and proliferation by reducing PD-L1 expression." (PMID 37928424, 2023). "Moreover, loss of SLC35C1 also decreased cell viability of H1299 cells, suggesting that expression of SLC35C1 is required for lung cancer cell proliferation." (PMID 37928424, 2023). "SLC35C1 can be considered as a potential novel target for lung cancer treatment." (PMID 37928424, 2023).